SPDYE12 (speedy/RINGO cell cycle regulator family member E12)
Synonyms: SPDYE12P
Tractability: No criterion of Open Targets' tractability assessment is met for any kind of drug.
Gene: Protein-coding gene on chromosome 7 (74,904,289 to 74,915,078, reverse strand). Ensembl gene ENSG00000184616.
Gene Ontology:
Molecular function: protein kinase binding
Genetic constraint (gnomAD): Loss-of-function variants: 1 observed, 5.32 expected, observed/expected ratio (o/e) 0.19, 90% interval 0.066 to 0.89. That is too few expected variants to judge how well the gene tolerates losing a copy. Missense variants: 24 observed, 59.81 expected, observed/expected ratio (o/e) 0.4, 90% interval 0.29 to 0.56. Synonymous variants: 7 observed, 21.98 expected, observed/expected ratio (o/e) 0.32, 90% interval 0.18 to 0.6.
Homologues: Orthologues: rat Spdye4 (50% identical), mouse Spdye4a (49% identical), mouse Spdye4b (44% identical). Paralogues in human: SPDYE10 (99% identical), SPDYE11 (99% identical), SPDYE17 (99% identical), SPDYE8 (99% identical), SPDYE9 (99% identical), SPDYE13 (99% identical), SPDYE14 (99% identical), SPDYE15 (99% identical), SPDYE3 (89% identical), SPDYE18 (84% identical), SPDYE16 (84% identical), SPDYE2 (84% identical), and 6 more.